ADAT2 (adenosine deaminase tRNA specific 2)
Description:
Catalytic subunit of the tRNA-specific adenosine-34 deaminase complex, composed of the ADAT2 catalytic subunit and the ADAT3 regulatory subunit, which deaminates adenosine-34 (the first, also called wobble position of the anticodon) to inosine in many tRNAs. Inosine-34 allows the decoding of 3 different nucleotides at the third position of mRNA codons, as inosine is able to pair with U, C, and A. Binding of the ADAT2-ADAT3 complex to tRNA is mediated by the N-terminus of ADAT3 which rotates with respect to the catalytic domain of the complex, formed by ADAT2 and the ADAT3 C-terminal domain, to position the tRNA anticodon stem-loop correctly in the ADAT2 active site. The ADAT2-ADAT3 complex is required for radial migration of projection neurons in the developing brain cortex, and the catalytic activity of the complex is necessary for this function.
Synonyms: DEADC1; dJ20N2.1; TAD2; dJ20N2
Tractability: Small molecule: it has a binding pocket of medium quality. PROTAC: ubiquitination databases record sites on it.
Gene: Protein-coding gene on chromosome 6 (143,422,832 to 143,450,695, reverse strand). Ensembl gene ENSG00000189007.
Subcellular location: Nucleus; Cytoplasm
Subcellular location (Human Protein Atlas): Golgi apparatus; Cytosol; Nucleoplasm
Pathways (Reactome):
Metabolism of RNA: tRNA modification in the nucleus and cytosol
Gene Ontology:
Molecular function: protein binding; tRNA-specific adenosine-34 deaminase activity; hydrolase activity; tRNA-specific adenosine deaminase activity; zinc ion binding
Biological process: tRNA wobble adenosine to inosine editing
Cellular component: nucleus; cytoplasm; nucleoplasm
Genetic constraint (gnomAD): Loss-of-function variants: 23 observed, 24.58 expected, observed/expected ratio (o/e) 0.94, 90% interval 0.67 to 1.33. The upper end of that interval is the gene's LOEUF score, 1.33, which puts it in group 5 of 6, group 1 being the genes least tolerant of losing a copy. Missense variants: 219 observed, 253.97 expected, observed/expected ratio (o/e) 0.86, 90% interval 0.77 to 0.96. Synonymous variants: 76 observed, 92.15 expected, observed/expected ratio (o/e) 0.82, 90% interval 0.68 to 1.
Homologues: Orthologues: chimpanzee ADAT2 (99% identical), macaque ADAT2 (98% identical), pig ADAT2 (93% identical), dog ADAT2 (93% identical), rabbit ADAT2 (93% identical), mouse Adat2 (89% identical), guinea pig ADAT2 (82% identical), rat Adat2 (70% identical), zebrafish adat2 (69% identical), tropical clawed frog adat2 (65% identical), Drosophila melanogaster CG5292 (39% identical), Caenorhabditis elegans JC8.4 (38% identical), and 4 more. Paralogues in human: ADAT3 (26% identical).
Diseases named in the same sentence as ADAT2 in open-access papers:
ADAT2 is named in the same sentence as 21 diseases in open-access papers, as found by Europe PMC text mining. Sharing a sentence is not in itself a finding about the gene and the disease. The quoted sentences say what the papers report.
breast carcinoma (3 papers, 2020 to 2025). "Moreover, increased ADAT2 mRNA level is associated with poor prognosis in breast cancer patients and ADAT protein levels were found by immunohistochemistry staining to be higher in BRCA1 mutant compared with BRCA1 wild-type breast tumors." (PMID 40907939, 2025). "By further analysing above EMT-related RBPs and AS in breast cancer tissues in TCGA, it was found that the expression levels of ADAT2, C2orf15, SRP72, PAICS, RBMS3, APOBEC3G, NOA1, ACO1 and the AS of TNC and COL6A3 were significantly correlated with the prognosis of breast cancer patients." (PMID 38783078, 2024). "We constructed a risk model based on the expression levels of these RBPs and found that ADAT2, C2orf15, SRP72, PAICS, RBMS3, APOBEC3G, NOA1, and ACO1 could be used for risk assessment in terms of breast cancer prognosis." (PMID 38783078, 2024).
breast tumors (3 papers, 2020 to 2025). "Our analysis shows a correlation between the high level of ADAT2 and the BRCA1 deficiency among BRCA1 deficient breast tumor samples." (PMID 32290274, 2020). "Thus, ADAT2 up-regulation observed upon BRCA1 inactivation in breast tumors exposes A34-to-I34 editing as a novel tRNA modification that is altered in cancer." (PMID 32290274, 2020). "Given the functional implications of BRCA1 inactivation on the translation of ADAT2, CCNL2, DBF4B, and TRIM45, we wondered whether the levels of these proteins were correlated to BRCA1 status in breast tumors." (PMID 32290274, 2020).
colorectal cancer (2 papers, 2023 to 2025). A primary or metastatic malignant neoplasm that affects the colon or rectum. "Although this is the first time ADAT2 has been linked to colorectal cancer, our data and literature information make ADAT2 (as well as FUCA2.rs11155297) interesting candidates for future studies in colorectal cancer progression and prognosis." (PMID 36998434, 2023). "In further support of this widespread oncogenic role, a previous study found that ADAT2-depletion led to decreased proliferation of HeLa (cervical carcinoma) and HT-29 (colorectal carcinoma) cells." (PMID 40907939, 2025).
Intellectual disability (2 papers, 2021 to 2024). "Although overexpression of ADAT2 has been shown to correct some of the defects in ADAT3 variant patients with intellectual disability, the level of inosine at the tRNA wobble position is tightly regulatedin vivo." (PMID 39034823, 2024). "A founder mutation in the ADAT3 N-terminal domain, which causes intellectual disability, does not affect tRNA binding despite the structural changes it induces but most likely hinders optimal presentation of the tRNA anticodon-stem-loop to ADAT2." (PMID 34057470, 2021). "Therefore, increasing the amount of I34-tRNA by increasing the level of ADAT2/3 may not be an effective therapy for curing intellectual disability." (PMID 39034823, 2024).
autism (1 paper, 2025). Persistent deficits in social interaction and communication and interaction as well as a markedly restricted repertoire of activity and interest as well as repetitive patterns of behavior. "Similarly, in the autism cohort, a de novo rare expanded TR was identified as a heSTR within the 3′UTR of ADAT2." (PMID 40446031, 2025).
colon cancer (1 paper, 2023). "It has previously been reported that low levels of ABI1 and high levels of ADAT2 or ISLR, result in an increase in extracellular matrix (ECM) degradation, migration, and cell invasion in colon cancer." (PMID 37158593, 2023).
liposarcoma (1 paper, 2025). A usually painless malignant tumor that arises from adipose tissue. "Here we show that the genes encoding the ADAT2/3 deaminase complex, responsible for A-to-I tRNA editing in humans, are commonly amplified and/or overexpressed in several tumor types including liposarcoma (LPS)." (PMID 40907939, 2025). "This study showed that the ADAT2/3 genes encoding the A-to-I tRNA editing complex are commonly amplified and/or overexpressed in cancer, and that ADAT2/3-depletion inhibits cancer cell growth hallmarks and tumorigenicity in human Liposarcoma cell lines." (PMID 40907939, 2025). "Although this study focused on human Liposarcoma, it is likely that the identified oncogenic function of ADAT2/3 is applicable to a broad range of different cancer types." (PMID 40907939, 2025). "We observed that sarcoma tumors, and specifically liposarcomas, are the cancer types that present the highest level of genetic amplification of the ADAT2 and ADAT3 loci." (PMID 40907939, 2025). "Among the sarcoma group, frequent amplification of ADAT2 and ADAT3 genes is observed in the dedifferentiated liposarcoma (LPS) subset." (PMID 40907939, 2025).
melanoma (1 paper, 2016). A malignant, usually aggressive tumor composed of atypical, neoplastic melanocytes. "In addition, we identify five genes (ALG12, GUSB, RPLP0, KRBA2, and ADAT2) that are stably expressed in melanoma cells independent of the presence of T cells or the T cell-derived cytokines IFNγ and TNFα." (PMID 27625650, 2016).
neuroblastoma (1 paper, 2021). Neuroblastoma (NB) is the most common solid, extracranial childhood tumor. "We first verified by transfection experiments in a N2A neuroblastoma cell line that WT ADAT2 and ADAT3 as well as their mutants were similarly expressed." (PMID 34057470, 2021).
Obesity (1 paper, 2015). Accumulation of substantial excess body fat. "And in the groups with diet-induced-obesity (OB), both adenosine monophosphate deaminase 2 (Ampd2) and adenosine deaminase (Adat2) were up-regulated." (PMID 26609465, 2015).
sarcoma (1 paper, 2025). A usually aggressive malignant neoplasm of the soft tissue or bone. "More detailed examination of TCGA datasets revealed that ADAT2 and ADAT3 mRNA expression is elevated in sarcomas compared with normal tissue samples." (PMID 40907939, 2025).
tumor (3 papers, 2020 to 2026). "Taken together with our findings that ADAT2 and ADAT3 mRNA expression levels are elevated in most tumor types compared with the corresponding normal tissues we propose that ADAT2/3 is broadly relevant in cancer." (PMID 40907939, 2025). "Moreover, gene copy number analysis showed that ADAT2 and ADAT3 loci are frequently amplified in several tumor types." (PMID 40907939, 2025).
cancer (2 papers, 2020 to 2025). A tumor composed of atypical neoplastic, often pleomorphic cells that invade other tissues. "Taken together, the cancer genetics and mRNA expression data implicate ADAT2 and ADAT3 in various cancers." (PMID 40907939, 2025). "To explore the requirement for ADAT2/3 in cancer cells, we used short harpin RNA (shRNA) constructs to specifically knock down ADAT2 and ADAT3 expression in human LPS cell lines." (PMID 40907939, 2025). "Our results uncover an oncogenic role of ADAT2/3 and identify this adenosine deaminase as a possible new pharmacologically tractable target for cancer therapy." (PMID 40907939, 2025). "Interestingly, gene ontology (GO) analysis showed that the genes with decreased translation efficiency in ADAT2-depleted cells are enriched in cancer-related processes including cell migration, cell proliferation, and cell motility." (PMID 40907939, 2025). "Our results showed that only the wild-type ADAT2 and not the catalytically inactive mutant form is able to rescue the malignant phenotype, thereby strongly supporting that the tRNA-editing activity of ADAT2 is responsible for the observed cancer cell growth phenotypes." (PMID 40907939, 2025). "We evaluated the effects of ADAT2 depletion on cancer cell growth and viability using a panel of cellular assays to measure several hallmarks of cancer and comparing our knockdown LPS cells to the parental cell line or cells transduced with a non-targeting shRNA (shGFP) as controls." (PMID 40907939, 2025). "Thus, ADAT2-mediated tRNA editing is required for codon-biased mRNA translation of growth-promoting genes in human cancer cells." (PMID 40907939, 2025). "Our results identify ADAT2/3 as a potential new cancer therapeutic target." (PMID 40907939, 2025). "Our data provide new insights into the role of the ADAT complex in gene expression and cancer and we propose that the ADAT2/3 deaminase could represent a new therapeutic target for cancer treatment." (PMID 40907939, 2025). "Moreover, in contrast to the LPS cancer cell lines, knockdown of ADAT2 in the non-cancerous human BJ fibroblasts did not cause any strong growth defects." (PMID 40907939, 2025). "We show that ADAT2 promotes the translation of oncogenic mRNAs that are enriched in ADAT-dependent codons, providing a selective advantage to cancer cells." (PMID 40907939, 2025). "We focused on ADAT2, CCNL2, DBF4B, and TRIM45 mRNAs that played key roles in cancer biology to demonstrate that alteration of their translational efficiency occurred via a BRCA1-dependent mechanism in cultured cells and in patient tumors." (PMID 32290274, 2020).
neurodevelopmental disorder (2 papers, 2021 to 2025). A behavioral and cognitive disorder with onset during the developmental period that involves impaired or aberrant development of intellectual, motor, or social functions. "Altogether, our results highlight the critical role of ADAT2/ADAT3 during cortical development and provide cellular and molecular insights into the pathogenic mechanisms underlying ADAT3-related neurodevelopmental disorders." (PMID 40120092, 2025). "Mutations in ADAT3, the catalytically inactive subunit of the ADAT2/ADAT3 complex, have been identified in patients presenting with severe neurodevelopmental disorders." (PMID 40120092, 2025).
ADAT2 also shares sentences with these, for which no sentence is quoted: infection (2 papers); asthma (1); cervical carcinoma (1); chronic obstructive pulmonary disease (1); diffuse large B-cell lymphoma (1); glioma (1); rhabdomyosarcoma (1).